CDK6 (cyclin dependent kinase 6)
Diseases named in the same sentence as CDK6 in open-access papers (continued):
Sharing a sentence is not in itself a finding about the gene and the disease.
lung cancer (continued). "We determined the CDK1, CDK4 and CDK6 mRNA expression alterations due to transfection with miR-143 and/or miR-506 in A549 lung cancer cells using quantitative real-time PCR (qRT-PCR)." (PMID 30002440, 2018). "Knockdown of ATDC reduced the protein levels of cyclin D1, p-Rb, CDK4, CDK6 and c-Myc in the 2 lung cancer cell lines with endogenous expression of ATDC." (PMID 23776433, 2013). "To investigate the mechanism of cell cycle progression regulated by ATDC in lung cancer, we examined the effect of ATDC on cyclin A, cyclin D1, cyclin E, CDK2, CDK4, CDK6, p-Rb and c-Myc in lung cancer cell lines." (PMID 23776433, 2013). "Furthermore, the up-regulation of the p21WAF1/CIP1 protein expression was observed along with the down-regulated expression of the CDK family of proteins (CDK4 and CDK6) in both lung cancer cells." (PMID 40941018, 2025). "Furthermore, hnRNP A2/B1 was also reported to promote miR-506-mediated CDK6 silencing by modulating the 3′UTR stem structure of CDK6 mRNA to facilitate AGO2 binding in lung cancer cells." (PMID 38689093, 2024). "Taken together, MEG8 could enhance progression of lung cancer through regulation of miR-107/CDK6 axis and activation of Rb/E2F3 pathway." (PMID 36114498, 2022). "Furthermore, the lung cancer cells co-transfected with si-CDK6 and miR-34a exhibited the lowest viability (P < 0.05, P < 0.01 respectively)." (PMID 33796457, 2021). "KDM4B has previously been shown to regulate CDK6 in bladder and lung cancer cells." (PMID 33917420, 2021). "Importantly, the si-CDK6-transfected lung cancer cells showed a significant reduction in the viability of cells compared to si-NC-transfected or miR-NC-transfected cells." (PMID 33796457, 2021). "Moreover, it has been reported before our study that both Cyclin D1 and CDK6 worked as downstream of Akt signaling pathway in the regulation of lung cancer and colorectal cancer." (PMID 33902600, 2021). "Moreover, TRIM59 is involved in lung carcinoma growth and invasion through the induction of CDK6 expression and EMT progression by activation of the ERK pathway." (PMID 30515965, 2019). "Therefore, future studies will be required to elucidate the precise mechanisms involved in the downstream molecules of PTEN, YY1 and CDK6 that could contribute to the miR-34a-mediated suppression of lung cancer progression." (PMID 33796457, 2021). "Given the critical role of CDK6 in lung cancer progression, XWLC-05 and NCI-H157 cells were co-transfected with CDK6 siRNA and miR-34a to elucidate whether CDK6 is involved in miR-34a-mediated inhibitory effect on lung cancer cell progression in the present study." (PMID 33796457, 2021). "In conclusion, this study demonstrates that components of the TIMM8A-TIMM13 complex exhibit elevated expression and potentially contribute to disease progression and poor outcomes in lung cancer patients through upregulation of CCND1 and CDK6." (PMID 40918471, 2025). "Immunohistochemical staining (IHC) experiments on clinical lung cancer tissues using tissue microarrays demonstrated a positive correlation between YTHDF1 and its downstream proteins, CDK6 and MAP3K6." (PMID 40278596, 2025). "Our study reveals that TIMM8A-TIMM13 complex, localized in the mitochondrial intermembrane space, drives lung cancer cell proliferation by upregulation of CCND1 and CDK6, thereby accelerating G1/S transition." (PMID 40918471, 2025). "This indicates that the expression of CDK6 and MAP3K6 was elevated during the transformation of normal cells into lung cancer cells." (PMID 40278596, 2025). "Studies on other malignancies, including adrenocortical carcinoma, osteosarcoma, lung cancer, and nasopharyngeal carcinoma, have demonstrated overexpression of CDK4 and CDK6, which promote tumor progression and poor prognosis." (PMID 40304827, 2025). "Reduced levels of CDK4, CDK6, and pRB coincided with the elevated levels of p21 after SAHA treatment in lung cancer cells confirmed cell cycle arrest, as shown in Western blot analysis." (PMID 40941018, 2025).
lung cancer (continued). "In non‐small cell lung cancer cells, Amentoflavone treatment significantly increases the cell population at the G1/G0 phase by decreasing the expression of cyclin D1, CDK4, and CDK6 in both H358 and H1299 cells." (PMID 38842135, 2024). "Therefore, further exploration of the mechanisms underlying CDK6 overexpression and the development of combination strategies to downregulate CDK6 expression have significant clinical value for overcoming CDK4/6i resistance in hormone-independent cancers, such as lung cancer." (PMID 37452037, 2023). "However, future studies are required on the precise regulatory network involved in the downstream molecules of PTEN, YY1, and CDK6 that could contribute to miR-34a-mediated tumor suppression for the clinical treatment of lung cancer in Gejiu and Xuanwei County, Yunnan Province." (PMID 33796457, 2021). "High levels of both miR-550a-3-5p and high metastatic lung cancer cell-derived exosomes markedly upregulated cleaved-PARP protein expression while downregulating pRB, CDK6, YAP1, CTGF, and CYR61 protein expression." (PMID 34530822, 2021). "We further explored the regulatory mechanisms between miR-34a and its downstream CDK6, PTEN, and YY1 to try to find the specificity and similarity of lung cancer in tin miners in Gejiu County and farmers in Xuanwei County compared to other NSCLC regions." (PMID 33796457, 2021). "Therefore, we conclude that YTHDF1 regulates CDK6 and MAP3K6 through m6A in B[a]P-induced HBE-P35 and A549 cells, providing a potential target for lung cancer treatment." (PMID 40278596, 2025). "Therefore, by combining TMT labeling-based proteomic analysis with previous findings, we explored the roles of CDK6 and MAP3K6 in lung cancer development and the relationship between YTHDF1, CDK6, and MAP3K6." (PMID 40278596, 2025). "Furthermore, the combined application of miR-506 and miR-143 in the treatment of lung cancer LC and PC synergistically downregulates CDK1, CDK4, and CDK6, blocking both the G1/S and G2/M transitions and inducing robust apoptotic activity." (PMID 40248198, 2025). "Next we revealed that miR-34a overexpression suppressed lung cancer growth and metastasis partially via increasing PTEN but reducing CDK6 expression that might lead to subsequent inactivation of PI3K/AKT pathway." (PMID 33796457, 2021). "The data are also consistent with our unpublished findings that artemether inhibited the malignant biological behaviors of lung cancer cells portionially via enhancing miR-34a expression, as well as reducing CDK6 expression (data not shown)." (PMID 33796457, 2021). "Sencond, XWLC-05, YTMLC-90, and H157 cells were transfected with pGCMV/EGFP-hsa-miR-34a or pGCMV/EGFP-hsa-miR-NC plasmids to demonstrate whether high expression levels of miR-34a correlated with the expression of PTEN, CDK6, and YY1 in lung cancer." (PMID 33796457, 2021). "To further verify the role of NDUFA4 in the growth and metastasis of lung cancer cells, we detected the expression of cell-growth-related molecules including CDK2, CDK3, CDK4, and CDK6, as well as metastasis-related molecules including CXCR4, E-Cadherin, MMP2, MMP3, and MMP9, respectively." (PMID 28325285, 2017). "In lung cancer, miR-377-5p inhibits cell development and regulated cell cycle distribution and epithelial to mesenchymal transition (EMT) by targeting AKT144 and reduces cell proliferation, promotes apoptosis in non-small lung cancer by targeting CDK6 and AEG-145,46." (PMID 32814765, 2020). "Additionally, YAP1 was identified as the target gene of exosomal miR-550a-3-5p, and miR-550a-3-5p may regulate the growth and migration of HBMECs by mediating YAP1, cleaved-PARP, pRB, CDK6, CTGF, and CYR61 protein expression, thus controlling brain metastasis of lung cancer." (PMID 34530822, 2021).
pancreatic cancer (49 papers, 2009 to 2025). "Altogether, our research provided further proof for the action of CDK6 in cancer progression, suggesting that nc‐RNA‐mediated high expression of CDK6 is associated with patient outcomes and immune invasion in pancreatic cancer." (PMID 36457244, 2023). "Overall, we elucidated high CDK6 expression in many kinds of human cancers by bioinformatic analysis and associated with poor prognosis for pancreatic cancer." (PMID 36457244, 2023). "Overall, these results established that nc‐RNA‐mediated high expression of CDK6 is associated with patient outcomes and immune invasion in pancreatic cancer." (PMID 36457244, 2023). "On the contrary, CDK4/CDK6 inhibitors have even been shown to sensitize RAS G12V-mutated cells against chemotherapeutic agents in pancreatic cancer." (PMID 35804842, 2022). "Treatment of pancreatic cancer cells with pristimerin also resulted in G1-phase arrest which was strongly associated with a marked decrease in the level of cyclins (D1 and E) and cyclin-dependent kinases (cdk2, cdk4 and cdk6 ) with concomitant induction of WAF1/p21 and KIP1/p27." (PMID 22952775, 2012). "For example, elevating miR-107 levels in MiaPACA-2 and PANC-1 cells led to reduced cell growth in vitro, linked to the suppression of cyclin-dependent kinase 6 (CDK6), a potential target of miR-107 in pancreatic cancer." (PMID 38302631, 2024). "miR-3613-5p was identified as a tumor repressor in pancreatic cancer cells by targeting cyclin-dependent kinase 6 (CDK6), thus regulating the cell cycle." (PMID 39591475, 2024). "This study found that miR-3613-5p regulated CDK6 expression and that downregulating 3613-5p in pancreatic cancer cells led to faster scratch wound closure and accelerated transwell invasion capacities." (PMID 36842089, 2023). "On the other hand, miR-34a which was shown to be upregulated in pancreatic cancer and silences NOTCH, BCL2, and CDK6 mRNAs, is associated with better survival." (PMID 37686149, 2023). "In order to study the function of CDK6 in pancreatic cancer cells, the siRNA for silencing CDK6 were transfected into MIA PaCa‐2 cells." (PMID 36457244, 2023). "Downregulation of CDK6 leads to inhibition of pancreatic cancer cell metastatic capacity, whereas increased CDK6 expression was observed in pancreatic cancer clinical samples and was associated with poor prognosis." (PMID 37124502, 2023). "miR-21 which was shown to be upregulated in pancreatic cancer and silences PTEN, PDCD4, IL-6R, and CDK6 mRNAs is associated with worse survival." (PMID 37686149, 2023). "In 2008, inactivation of miR-34a by CpG methylation was described in prostate, breast, lung, colon, kidney, and pancreatic carcinoma cell lines; re-expression of this miRNA induced senescence and cell cycle arrest by targeting cyclin-dependent kinase 6 (CDK6)." (PMID 33809566, 2021). "In light of this, we analyzed relevant genomic data and observed the opposite effects of CDK4 and CDK6 on pancreatic cancer prognosis." (PMID 33282875, 2020). "It has been reported that epigenetic silencing of miR-107 can regulate the expression of cyclin-dependent kinase 6 in pancreatic cancer; while interfering miR-409-3p promotes tumour growth, the epithelial-to-mesenchymal transition (EMT) and bone metastasis." (PMID 25880988, 2015). "Conspicuously, we notice that 5 genes (CDK6, E2F3, CCND1, SMAD4 and CDKN1B) are associated with cell cycle, colorectal cancer, pancreatic cancer, chronic myeloid leukemia, and small cell lung cancer in the cluster of Group A." (PMID 26221171, 2015). "Re-expression of miR-34a in a pancreatic cancer cell line induced senescence and cell cycle arrest by targeting CDK6, indicating that miR-34a represents a tumor suppressor gene which is inactivated by CpG methylation in pancreatic cancer." (PMID 23056009, 2012). "Moreover, as a member of the cell cycle-regulated kinase family, CDK6 is an important and actionable target in pancreatic cancer." (PMID 37540586, 2024).
pancreatic cancer (continued). "Similarly, the higher expression of the RB1 and CDK6 genes was correlated with poor overall survival in pancreatic cancer patients." (PMID 39123441, 2024). "The potential mechanism of CDK6 affecting immune cells in pancreatic cancer was discussed." (PMID 36457244, 2023). "Conversely, sequential treatment with CDK6 inhibitors following DNA-damaging chemotherapy was shown to improve the therapeutic effect in pancreatic cancer, which was due to the action of CDK6 inhibitors on the homologous recombinant proteins responsible for repairing chromosome damage." (PMID 35480115, 2022). "All compounds with shorter linker degrade CDK6 partly, while the PROTAC containing the longest linker (23a) selectively degraded CDK6 at the single dose of 500 nM in pancreatic cancer MiaPaCa2 cells with respect to other cyclin-dependent kinases including CDK4." (PMID 33803309, 2021). "The results demonstrated that silencing circSEC24A expression resulted in protein downregulation of CDK4, CDK6 and Cyclin D1, indicating that inhibited circSEC24A could negatively modulate pancreatic cancer cell proliferation." (PMID 34906151, 2021). "The expression level of CDK6 is elevated in pancreatic cancer, medulloblastoma, and GC." (PMID 30530570, 2019). "Moreover, miR124 known to regulate multiple proliferation-related genes in pancreatic cancer cells such as cyclin-dependent kinase 6, Cyclin A2, forkhead box A2 and solute carrier family 16, member 1 (SLC16A1)." (PMID 27240340, 2016). "GAS5 silencing increases—and ectopic GAS5 lncRNA expression decreases—CDK6 mRNA and protein levels in cell lines; a similar, inverse relationship between GAS5 and CDK6 levels has been reported in bladder and pancreatic cancer tissues, suggesting that this interaction is operative in vivo." (PMID 26198250, 2015). "In addition, CDK6 was also correlated with the histological stage of pancreatic cancer (p < 0.05)." (PMID 36457244, 2023). "However, the precise role of CDK6 in Pancreatic cancer (PC) remains obscure." (PMID 36457244, 2023). "This study demonstrates that knockdown/overexpression of CCNI2 in pancreatic cancer cells can downregulate/upregulate the expression of CDK5 and CDK6." (PMID 37540586, 2024). "We studied the effects of the combination of Abe, a CDK4/CDK6 inhibitor, and Pan, a pan-HDAC inhibitor (HDACi), on pancreatic cancer cells." (PMID 39123441, 2024). "Here, we demonstrated that when expressed in p16-null pancreatic cancer cells, p16-L16R had little ability to suppress the cell cycle and exhibited decreased binding to CDK4 and CDK6 compared with p16-WT." (PMID 33823155, 2021). "The most significantly identified enriched pathway were about the pancreatic cancer (P = 0.0011), which four target genes (CDC42, MAPK1, SMAD3, and CDK6) were predicted to be involved in." (PMID 33178707, 2020). "In pancreatic cancer the expression level of GAS5 has been verified to be obviously reduced in pancreatic cancer tissues, and GAS5 upregulation represses cell proliferation by suppressing expression of cyclin-dependent kinase 6 (CDK6) in vitro and in vivo." (PMID 31182630, 2019). "We previously demonstrated that GSK3β sustains expression of CDK4, CDK6, and cyclin D1, which results in phosphorylation-dependent inactivation of RB cell cycle regulator, in CRC and pancreatic cancer cells." (PMID 29568361, 2018). "We also found that DHA down-regulated cdks and cyclins, such as Cdk4, Cdk6, and cyclin E, which play essential roles in the regulation of cell cycle progression; DHA thus increased G0/G1 cell cycle arrest in pancreatic cancer cells." (PMID 27613829, 2016). "Down-regulation of Cdk4, Cdk6, E2F3, and E2F1 expression increases G0/G1 cell cycle arrest in pancreatic cancer cells." (PMID 27613829, 2016).
pancreatic cancer (continued). "Cdk4, Cdk6, E2F3, and E2F1 play key roles in the regulation of cell cycle progression in pancreatic cancer." (PMID 27613829, 2016). "The observed inhibitory effects of pristimerin on cyclin D1, cyclin E, cdk2, cdk4 and cdk6, along with its upregulating effects on WAF1/p21 and KIP1/p27 in pancreatic cancer cells suggest its potential in disruption of the uncontrolled cell cycle progression." (PMID 22952775, 2012). "In all four pancreatic cancer cell lines tested, we found decreased expression of cell cycleproteins, including E2F1, Cyclin D1, Cyclin E, Cdk2, Cdk4 and Cdk6, and increased expression of p21 and p27." (PMID 23028659, 2012). "Overexpression of AP-2α in pancreatic cancer cells was shown to reduce tumor growth through an altered expression pattern of cell cycle-controlling factors such as CDK-4, CDK-6, Cyclin-G1, p27kip1 and p57kip2." (PMID 20805990, 2010). "Recently, overexpression of AP-2α in pancreatic cancer cells was shown to reduce tumor growth through an altered expression pattern of cell cycle-controlling factors such as CDK-4, CDK-6, cyclin-G1, p27kip1 and p57kip2." (PMID 20805990, 2010). "The concomitant effects of this therapy on CDK6 in more relevant physiological models of pancreatic cancer can, therefore, not be discounted." (PMID 33282875, 2020). "Surprisingly, we found that four crucial microRNAs (miR-34a-5p, miR-195-5p, miR-30c-5p, and miR-130b-3p) regulated the expression of many mRNAs (Cdk4, Cdk6, VEGF, IKKα, MEK1, E2F3, Rac1, E2F1, ERK1, and CDC42) and their proteins, and thus were crucial to the anti-pancreatic cancer effects of DHA." (PMID 27613829, 2016). "To determine protein levels of the mRNAs modulated by DHA via microRNAs, we next examined Cdk4, Cdk6, VEGF, IKKα, MEK1, E2F3, Rac1, E2F1, and CDC42 protein levels, which affect growth, inhibit angiogenesis, and promote apoptosis in DHA-treated and vehicle-treated pancreatic cancer cells." (PMID 27613829, 2016).